IL17RC (interleukin 17 receptor C)
Diseases named in the same sentence as IL17RC in open-access papers (continued):
Sharing a sentence is not in itself a finding about the gene and the disease.
rubella (1 paper, 2023). A viral infection caused by the rubella virus. "In rubella, including five in whole blood (JAGN1, RRP12, RP11-452K12.7, CASP7, and AP3S2), four in the lung tissue (IL17RC, FAM86HP, AMACR, and RRP12), and four in the transformed fibroblast cells (PPP2R1B, C11orf1, DLAT, and TMEM117)." (PMID 37020999, 2023).
sarcoidosis (1 paper, 2014). Sarcoidosis is a multisystemic disorder of unknown cause characterized by the formation of immune granulomas in involved organs. "Sarcoidosis has been suggested as a Th17 disease and IL17RC is critical in mediating IL-17 induced tissue damage." (PMID 24885153, 2014). "In addition, IL-17RC appeared only in the retinal tissue of the patient with clinically active sarcoidosis." (PMID 24885153, 2014). "In addition, in the eye with clinically active sarcoidosis, IL17RC RNA expression averaged at 108.1 fold higher in the retinal inflammatory lesion but only 14.2 fold higher in the normal retina compared to the normalization with beta-actin mRNA level." (PMID 24885153, 2014). "However, we only found a minimal induction of IL-17RC in response to IL-17 treatment on CD8+ T cells from sarcoidosis patients." (PMID 24885153, 2014). "It is unclear how IL-17RC was induced in CD8+ T cells in sarcoidosis patients." (PMID 24885153, 2014). "Importantly, we found sustained expression of IL-17RC protein and transcripts in the retinal tissue with granulomatous inflammation of clinically active but not quiet sarcoidosis patients." (PMID 24885153, 2014).
skin papilloma (1 paper, 2022). A benign papillary neoplastic growth on the skin composed of epithelial cells and a fibrous stalk. "The knockout of Il17rc completely abolished the formation of skin papilloma." (PMID 36009523, 2022).
skin tumors (1 paper, 2022). "Il17ra(T779A)-KI significantly reduced tumor incidence, and Il17rc-KO completely prevented the development of skin tumors, which supports the view that IL17 signaling promotes tumorigenesis." (PMID 36009523, 2022).
tendinopathy (1 paper, 2025). "The IL-17A receptor heterodimer subunits IL17RA and IL17RC were constitutively expressed with medium abundance; however, IL17RA and IL17RC receptor expression was not linked to the upregulated expression of IL17A and was not significantly altered in tendinopathy." (PMID 39988349, 2025).
thromboangiitis obliterans (1 paper, 2022). A rare inflammatory non-necrotizing vascular disease affecting the small- and medium-sized arteries and veins of the upper and lower extremities characterized by endarteritis and vaso-occlusion due to occlusive thrombus development. "Although it is not specific for LEAD, a case-control GWAS of 177 patients with thromboangiitis obliterans (TAO) identified three SNPs (rs376511 in the IL17RC gene, rs7632505 in the SEMA5B gene, and rs10178082 in the RPA3 gene) that were significantly associated with TAO in the Uighur population." (PMID 36142394, 2022).
tongue cancer (1 paper, 2019). A malignant neoplasm affecting the tongue. "Interestingly, the mRNA of the IL-17F receptors (IL-17RA and IL-17RC) were decreased in both HSC-3 and SCC-25 tongue cancer cell lines compared to normal HOKs." (PMID 31083515, 2019).
tumor (21 papers, 2008 to 2025). "As our survival analyses indicate an association of both IL17A mRNA expression in tumor tissue and IL‐17RC levels in ascites with a short survival, the pro‐tumorigenic functions of IL‐17A appear to predominate in determining the clinical outcome." (PMID 38566518, 2024). "We observed that in populations with T lymphocytes-infiltrating LUAD tissues that expressed high levels of IL-17RC messenger (m)RNA had poorer prognoses, particularly in those with a high tumor mutation burden." (PMID 33802737, 2021). "Genes encoding cognate receptors Il17ra and Il17rc were relatively increased, respectively, in immune cells (particularly neutrophils and macrophages) and Basal tumor cells." (PMID 34408137, 2021). "Here, we describe a novel molecular mechanism underlying IL-17RC-controlled tumor-specific proliferation." (PMID 28562353, 2017). "Surprisingly, the loss of IL-17RC expression in 4T1 cells directly promoted tumor cell growth in culture." (PMID 28562353, 2017). "In contrast to the existing dogma that IL-17RC-dependent signaling activates the JNK pathway, IL-17RC KD in both tumor cell lines caused aberrant expression and activation of different JNK isoforms along with markedly diminished levels of the ubiquitin-editing enzyme A20." (PMID 28562353, 2017). "This is consistent with a recent report that IL-17RC is a critical determinant of IL-17–mediated response in tumor cells." (PMID 40749055, 2025). "Among the tumor genes, we note some that have been implicated in mTOR activation (MAP2K6 and IL17RC) or inhibition (GJB3) and were upregulated or downregulated, respectively, in everolimus-adapted (LT) tumors." (PMID 39541354, 2024). "We then examined the surface expression levels of IL-17RA and IL-17RC on two CTL subsets of tumor-infiltrated lymphocytes (TILs) based on the surface markers of Slamf6 and Tim3." (PMID 37605139, 2023). "The treatment with centrinone slightly exacerbated tumor burden in WT male mice, but the condition was improved by Il17ra(T779A)-KI and Il17rc-KO." (PMID 36009523, 2022). "Even though the proliferation of the epidermis in both male and female mice was significantly induced by DMBA/TPA among WT, Il17ra(T779A)-KI, and Il17rc-KO mouse strains, Il17ra(T779A)-KI alleviated tumor formation and Il17rc-KO totally abolished it." (PMID 36009523, 2022). "Further analyses of clinical datasets revealed correlations of IL-17 receptor A (IL-17RA) and IL-17RC expressions with a poor prognosis of LUAD patients with a smoking history or with higher levels of tumor-infiltrating lymphocytes." (PMID 33802737, 2021). "Despite the expression of IL-17RA and IL-17RC on 4T1 TNBC tumor cells, 4T1 cells transduced with AdIL-17A and Addl showed similar growth kinetics in vitro, suggesting that IL-17A stimulation has a little direct effect on the growth of 4T1 TNBC cells." (PMID 32770025, 2020). "Previous reports have suggested that IL-17 signals through interactions with transmembrane receptors composed of IL-17RA and IL-17RC heterodimers induce a broad tissue response at the site of inflammation and increase pro-tumor activity on tumor cells." (PMID 29515773, 2018). "Taken together, our data suggest that IL-17RC silencing induces tumor-specific expression and activation of JNK1 and JNK2 isoforms, which have opposing roles in controlling downstream c-Jun activity and c-Jun-dependent homeostatic proliferation." (PMID 28562353, 2017). "Not only does IL-1B appear positively correlated with MAP17 in all tumors, other interleukins including IL-15, IL-18, IL-1A, IL-32 and IL-7 and interleukin receptors including IL-10RB, IL-17RC and IL-2RG appear in at least three of the tumor types." (PMID 29228712, 2017). "We demonstrate that IL-17RC is critically required for maintaining basal levels of the ubiquitin-editing enzyme A20, which represses homeostatic proliferation of tumor cells in a JNK1/JNK2 isoform-dependent manner." (PMID 28562353, 2017).
tumor (continued). "In summary, our study elucidates a previously uncharacterized tumor-suppression/evasion mechanism whereby the basal levels of anti-inflammatory A20 is controlled by IL-17RC." (PMID 28562353, 2017). "Moreover, we also indicated that T lymphocyte infiltration in the tumor microenvironment is critical for IL-17A-IL-17RA/IL-17RC-modulated LUAD progression." (PMID 33802737, 2021). "Notably, despite its impact on stress-induced apoptosis, IL-17RC-controlled homeostatic proliferation appears to ultimately dictate the invasiveness of tumor cells in vitro and in vivo." (PMID 28562353, 2017). "Depending on the endogenous activities of JNK1 and JNK2, IL-17RC-dependent signaling may either positively or negatively regulate homeostatic proliferation and invasiveness of tumor cells." (PMID 28562353, 2017). "Therefore, our data suggest that IL-17RC has divergent roles in controlling homeostatic proliferation and stress-induced apoptosis in different tumor types." (PMID 28562353, 2017). "Only a single large expansion detected in Il17rc was not tumour-associated." (PMID 40386410, 2025). "Importantly, the level of phospho-JNK in B16-RCKD and 4T1-RCKD clones was markedly attenuated by JNK2 and JNK1 shRNA, respectively, reinforcing the notion that IL-17RC silencing induces differential acquired-activation of distinct JNK isoforms in the two tumor cell lines." (PMID 28562353, 2017). "Furthermore, it is intriguing whether other non-IL-17R inflammatory receptors including TNFR, IL-1R and TLR may also control tumor-specific proliferation in a manner that we have demonstrated for IL-17RC." (PMID 28562353, 2017). "This study showed that the gene expression of IL-17RA, IL-17RC, and CXCR2 in tumor tissues was significantly higher than in normal tissues isolated from patients with BC." (PMID 38515019, 2024). "Most importantly, interleukin-17 receptor e (IL17RE), interleukin-17 receptor c (IL17RC), and FGFR3, all involved in the regulation of tumor microenvironment (TME), were found in this group." (PMID 35641998, 2022). "Collectively, our data demonstrate that IL-17RC silencing results in acquired JNK-activation in B16 and 4T1 cells but distinct c-Jun activities in the two tumor cell lines." (PMID 28562353, 2017). "Reduced IL-17RC expression can lead to aberrant JNK activation and altered tumor cell proliferation in a JNK-isoform-dependent manner." (PMID 28562353, 2017). "Il17ra(T779A)-KI did not alter tumor multiplicity, but Il17rc-KO significantly alleviated the growth of tumors." (PMID 36009523, 2022). "Interestingly, we found their receptors, IL17RA/IL17RC for IL17A/IL17F, IL10RB/IL22RA1 for IL22, and IL20RA/IL10RB for IL26, were upregulated in tumor cell than in normal epithelial cells." (PMID 35999201, 2022). "Consistent with tumor multiplicity, Il17rc-KO completely stalled tumor growth without any obvious gender difference." (PMID 36009523, 2022). "Pronounced tumor formation was observed in WT and Il17ra(T779A)-KI mice, but no tumors developed in the Il17rc-KO mice." (PMID 36009523, 2022). "Indeed, in the GSE51401 dataset, ICAM1 transcription level was negatively correlated with IL-17A level of tumor tissues and with IL17RC in TECs but not in NECs." (PMID 37605139, 2023). "Given that the IL-17RC silencing induced consistent JNK-activation with distinct c-Jun activities and inverse proliferation patterns in the two tumor models, we questioned whether IL-17RC silencing induced activation of different JNK isoforms in B16 and 4T1 cell lines." (PMID 28562353, 2017). "Cyclin E proteolysis might be a tumor specific mechanism as IL-17A failed to up-regulate the generation of LMW-E forms in the non-transformed mammary epithelial MCF10A cells although these cells express significant levels of IL-17RA and IL-17RC." (PMID 26154409, 2015).
infection (12 papers, 2012 to 2025). The state of being infected such as from the introduction of a foreign agent such as serum, vaccine, antigenic substance or organism. "It is worth noting that we used 100 PFU of infection via footpad inoculation to assess the susceptibility of IL17rc-/- mice, measuring viral load, cytokine profiles, and immune cell brain infiltration as described in our previous publications." (PMID 40632810, 2025). "In gilthead seabream, the expression profile in the HK was unaffected but, in the brain, il17rb, il17rd, and il17re-like were up-regulated, whereas il17rc was down-regulated to a significant extent at 1-day post-infection (dpi)." (PMID 38827125, 2024). "We found that the expression of eight genes, including Il18, Il36b, Il17rc, Tnfsf10, Tnfsf11, Tnfsf14, Tnfsf15, and Il1a, were closely correlated with the severity of HAdV-55 infection." (PMID 30787914, 2019). "While only 12.5% of animals survived when treated with PBS, 66.7% of animals treated with IL17RC SD12 were still living at day 8 post-infection." (PMID 23300439, 2012). "It is possible that IL-17RC expression could also be upregulated in human neutrophils under our experimental settings, i.e., pretreatment with IL-17A for 0.5 h and infection with live P. aeruginosa in the presence of human serum." (PMID 30455194, 2019). "Therefore, il17rc downregulation only after infection with RNA1-mutants could counteract the early immune response, preventing an increase in the disease severity due to a strong immune response." (PMID 34832544, 2021). "Therefore, the downregulation of il17rc later in the infection by RNA1-mutants could reduce inflammation, one of the main factors involved in the severity of the disease." (PMID 34832544, 2021). "On the other hand, at 3 days p.i., il17rc, involved in the JAK-STAT cascade, was only downregulated after the infection with both RNA1-mutants." (PMID 34832544, 2021). "Thus, lower eye disease in IL17RC−/− mice could be associated with the absence of neutrophils, leading to reduced IL-6 expression at the site of infection." (PMID 32516406, 2020). "Mice were treated with 7.5 mg/kg of IL17RC SD12 at day 0, day 1, and day 2 post-infection and monitored for disease symptoms." (PMID 23300439, 2012). "We first tested if the absence of IL-17RA or IL-17RC blocks CNS demyelination following infection with the HSV-IL-2 virus." (PMID 36817487, 2023). "Furthermore, the infection with the RNA1-mutants provoked the exclusive expression of pkr and the downregulation of il17rc." (PMID 34832544, 2021).
cancer (11 papers, 2015 to 2024). A tumor composed of atypical neoplastic, often pleomorphic cells that invade other tissues. "In our study, we have unexpectedly discovered a novel scenario in which aberrant activation of NF-κB and JNKs in cancer cells is acquired upon the loss of a pro-inflammatory molecule—IL-17RC, and an anti-inflammatory molecule—A20." (PMID 28562353, 2017). "Evidence suggests differential expression of IL-17RC protein isoforms in prostate cells and cancer tissues." (PMID 39906741, 2024). "In cancer tissues, 41.4% of samples showed moderate to strong positive IL-17RC expression whereas 100.0% of normal tissues displayed negative to weak expression." (PMID 36125689, 2023). "Once LAB colonizes in GC, it can potentially promote GC via 4 mechanisms: 1) via impact the release of interleukin-1β/17 A/22, 2) via IL-17RC/NF-ᴋB/NOX1 pathway, 3) via gastric inflammatory and cancer-associated genes TNF-α/Ptger4/Tgf-β, 4) via N-nitroso compounds and 5) ROS." (PMID 38075398, 2024). "Both IL-17RA and IL-17RC play essential roles in disease progression including cancer." (PMID 33802737, 2021). "Unclear, elevated levels of IL-17RC in CRPC; higher expression of IL-17F in cancers with higher histological grades." (PMID 37371647, 2023).
kidney disease (2 papers, 2023 to 2024). "We did not observe any relationship between the selected SNPs in genes coding for IL-17A, IL-17RA, IL-17RC, and miR-146a-5p and kidney disease risk, as their alleles/genotypes segregated similarly in patients and controls." (PMID 38792460, 2024). "IL-17RC has also been found to enhance proinflammatory function in kidney disease by regulating CD4+ T cells." (PMID 38045694, 2023).
neurodegenerative disease (2 papers, 2015 to 2022). A disorder of the central nervous system characterized by gradual and progressive loss of neural tissue and neurologic function. "IL-17RC serves as an essential subunit of the IL-17 receptor complex and mediates the signal transduction and proinflammatory activities of IL-17A and IL-17F, which have been implicated in autoimmune and neurodegenerative diseases." (PMID 26504591, 2015).
infectious disease (1 paper, 2023). A disorder directly resulting from the presence and activity of a microbial, viral, or parasitic agent in humans. "Consistent with previously reported IL-17RC-deficient patients, this patient had early-onset mucocutaneous candidiasis but without any other severe infectious diseases, including mucocutaneous S. aureus disease or autoimmune clinical signs." (PMID 37577484, 2023).
IL17RC also shares sentences with these, for which no sentence is quoted: benign prostatic hyperplasia (2 papers); acute GVHD (1); adolescent idiopathic scoliosis (1); alveolitis (1); Alzheimer disease (1); autoimmune polyendocrine syndrome type 1 (1); Blepharophimosis (1); Blindness (1); bullous pemphigoid (1); cervical cancer (1); chronic obstructive pulmonary disease (1); cystitis (1); dermatitis (1); diabetes (1); diabetic retinopathy (1); disc degeneration (1); Epicanthus inversus (1); glioblastoma (1); Granuloma (1); hemoglobinopathies (1); hepatocellular carcinoma (1); Hurler-Scheie syndrome (1); hyperplasia (1); Hypertension (1); inflammatory bowel disease (1); ischemic stroke (1); liver inflammation (1); lymphoma (1); nephrotic syndrome (1); non-small cell lung carcinoma (1).
A further 21 diseases each share a sentence with IL17RC in 1 paper.